CCL20 (C-C motif chemokine ligand 20)
Diseases named in the same sentence as CCL20 in open-access papers (continued):
Sharing a sentence is not in itself a finding about the gene and the disease.
infection (continued). "We also show that ~95% depletion of c-KIT transcript levels by siRNA treatment rescued EGR1, VCAM1, CCL20, and IL-8 gene expression in response to Y. enterocolitica WA infection in THP-1 cells, compared to infected control cells treated with non-targeting siRNA (si-CTL)." (PMID 24206648, 2013). "However, the effects on induction of ccl20, nos2 and odc were much more pronounced upon infection with the isolate GS than with WB and P15." (PMID 24228819, 2013). "Furthermore, IL-17 can induce CCL20 expression, which recruits Th2 cells to infection sites." (PMID 41257796, 2025). "Interestingly, we observed a significantly higher CCL20 release upon 24 h of infection by the MenW cc11 strain, which could be indicative of increased cell stress in this condition or of a strain-specific induction." (PMID 40586572, 2025). "Similarly, the expression of the tumor necrosis factor (TNF) gene and the CCL20 gene was downregulated two weeks after infection with M. gallisepticum strain Ap3AS, which may be attributed to the immunomodulatory effects of M. gallisepticum." (PMID 38474071, 2024). "The heightened colonization potential of this pathovar in CRC patients may result in increased levels of pro-inflammatory cytokine IL-8 and chemokine CCL20 in large intestinal epithelial cells, which can induce the recruitment of macrophages and dendritic cells to the infection site." (PMID 38939191, 2024). "Our results demonstrated that vaccination with pcHrp1 or pcHrp1+pcIL-34 could significantly trigger the expression of IL-8, CCL2, CXCL9, CXCL10, and CCL20, indicating that the chemokines were involved in the recruitment of neutrophils, monocytes, Th1 cells, and Th17 cells to the infection sites." (PMID 32231137, 2020). "In addition, a disruption of the chemoattractant axis CCL20/CCR6 in Il1a-/- mice could explain the reduced Th17 response after 30 days of infection." (PMID 31425553, 2019). "As airway epithelial cells have been shown to increase the expression of hBD2 and/or CCL20 in response to infection with several pathogens, we sought to determine whether infection with virulent B. abortus 2308 also increases the expression of hBD2 and CCL20 in these cells." (PMID 26448160, 2015). "Indeed, infection with the virulent strain also led to an increase in expression (1.5 to 2.3 fold) for most of the other pro-inflammatory mediators tested (CCL20, IL-6, IL-12p40, and IFN-γ) as well as to an upregulation (1.7 fold) of the antimicrobial LeukoP as compared to the UI control loops." (PMID 22675469, 2012). "As demonstrated here, the expression of IL-8/CXCL8, Gro-α/CXCL1, MCP-2/CCL8 and MIP-3α/CCL20 was compromised in LPS-stimulated IRAK4-deficient monocytes, suggesting a diminished recruitment of neutrophils, monocytes, lymphocytes, basophils and eosinophils to sites of infection." (PMID 20105294, 2010). "Infection of rhesus (Macaca mulatta) or cynomolgus (Macaca fascicularis) macaques with pathogenic SIV leads to the induction of multiple inflammatory chemokines in lymph nodes and spleen including: CXCL8; CXCL9, CXCL10, and CXCL11; CCL3, CCL4, CCL5; CCL2; CCL19; and CCL20." (PMID 19149556, 2009). "On the other hand, infection with SFV/TNFα specifically upregulated the amount of IL-6, CCL2, CCL3, CCL7 and CCL20 (p < 0.0001)." (PMID 40547518, 2025). "In the saline group, there was minimal DEG overlap between 3 and 7 DPI relative to the pre-infection time point, with only seven shared DEGs that enriched to leukocyte migration and response to interleukin-1 (CXCL8 and CCL20) gene ontology (GO) terms." (PMID 40576342, 2025). "Inflammatory chemokines, such as IL‐8, MIP‐1α/CCL3, and MIP‐3α/CCL‐20, act mainly by attracting monocytes, neutrophils, and other effector cells from the blood to sites of infection or tissue damage." (PMID 40101934, 2025). "Immunohistochemistry and flow cytometry revealed that CCL20-/- and CCR6-/- mice have impaired recruitment of T cells, especially CCR6+ T cells, to the site of infection." (PMID 40853122, 2025).
infection (continued). "Only six mediators, ADA, CXCL1, CCL20, MCP-3, PD-L2, and TNFSF14, differed between the “infection-free” and actively infected groups." (PMID 41387890, 2025). "Chemokines, including CXCL8, CCL20, and MIF, recruit immune cells, such as neutrophils, macrophages, and T cells, to sites of infection and inflammation and play critical roles in the immune response to pathogens (45, –, 48)." (PMID 41081505, 2025). "A larger overlap in DEGs was noted between the two time points in the infection group with 74 DEGs that enriched to processes involved in wound repair (HBEGF and MT2A) as well as immune responses to pathogens (CCL20, IL6, and SLAMF1)." (PMID 40576342, 2025). "Mast-cell-derived cytokines and chemokines facilitate the migration of dendritic cells (DCs; TNF-α and CCL20) and effector T cells (CXCL10/IP10 and CCL5/RANTES) to the infection site and draining lymph nodes." (PMID 40867663, 2025). "Of these, CCL20, CXCL10, CXCL1, CXCL8, and IL-18 showed higher levels compared to uninfected epithelium 24 h after infection." (PMID 40586572, 2025). "In our study on the early infection phase of FHV-1, the upregulation of CCL17, CCL20, and CXCL10 among these cytokines and chemokines, as well as that of TNF were observed, while there were no significant changes in IFNs." (PMID 39591303, 2024). "The observed infiltration of immune cells after infection with swH1N1 agrees with the upregulation of chemotactic factors (AMCF-II, CXCL8/IL8, CXCL2, CXCL10, and CCL20) and their receptors (CCR1 and CXCR2) at the transcriptional level." (PMID 39247193, 2024). "Compared with infection alone, H. influenzae and rhinovirus coexposure synergize with the respiratory epithelium to stimulate CXCL8 and CCL20 production, leading to more severe airway inflammation." (PMID 37305112, 2023). "In contrast, secretion of chemokines such as RANTES, MIP-3α (CCL20), MIP-1β (CCL4), and I-TAC (CXCL11) remained unaltered or moderately upregulated in the Usp25−/− cells upon infection." (PMID 37683630, 2023). "CCl20 and its receptor, CCR6, control the migration of dendritic cells and Th17 CD4+ T cells to the site of infection and inflammation." (PMID 37243277, 2023). "Viral burden, measured by TCID50, was similar in cells obtained from lean and obese individuals; however CCL20 and the injury mediator PAI-1 were significantly elevated in cells from obese individuals at 48 h post-infection (hpi)." (PMID 37680710, 2023). "While the levels of both mRNA and secreted protein for IL-1α and CXCL8 increased in response to infection, the levels of CXCL10 and CCL20 in the culture supernatant decreased." (PMID 37067432, 2023). "Similar to 12 h, genes significantly upregulated in the later stages of infection were cytokines or chemokines, such as CXCL1, CXCL2, CXCL3, CXCL8, CXCL10, and CCL20." (PMID 37211158, 2023). "P. micra infection was found to up-regulate the expression of IL-5 (P=0.0001), IL-8 (P=0.0001), CCL20 (P=0.0001), and CSF2 (P=0.0001) at 2 hr post-infection." (PMID 37218575, 2023). "Quantification of the expression of six inflammatory markers (IL-5, IL-8, IL-22, CCL20, TIMP1, CSF2) was carried out at 2, 24, and 48 hr post-infection." (PMID 37218575, 2023). "The combination treatment with both TMAO and CFT073 had significant additive effects on the release of CXCL11 and CCL20 and synergistic effects on the release of IL-8, CXCL1, and CXCL6 compared to CFT073 infection alone." (PMID 37111409, 2023). "Based on our observations, we propose a novel mechanism by which A. fumigatus melanin suppresses host innate immunity to promote infection by binding to and removing CXCL10 and CCL20 from the extracellular environment." (PMID 37067432, 2023).
infection (continued). "A more detailed analysis of DEGs indicated on a strong immune response in MKN-28 cells after 2-h infection based on increased transcription of IL1A, IL8, IL24, CXCL2, CXCL3 and CCL20." (PMID 37193047, 2022). "Nevertheless, pretreatment with 1,25(OH)2D3 significantly suppressed IL-19 and CCL20 mRNA expression and decreased p-NF-κB protein levels induced by PEDV at 24 h post-infection in IPEC-J2 cells." (PMID 36142545, 2022). "Infection with the als3Δ/Δ and ece1Δ/Δ single mutants induced significantly less secretion of CXCL8/IL-8, CCL20, IL-1α, and IL-1β than the wild-type parent strain." (PMID 33471869, 2021). "Moreover, infection of the Colon Chips with the pathogenic bacterium, Salmonella typhimurium, resulted in epithelial detachment, decreased tight junction staining, and increased release of chemokines (CXCL1, CXCL2, and CCL20) that closely mimicked changes previously seen in mice." (PMID 33777849, 2021). "VSV infection significantly induced the expression of seven chemokines (CCL3, CCL4, CCL5, CCL20, CXCL1, CXCL2, and CXCL3) by ~3- to 42-fold compared to mock infection." (PMID 34578166, 2021). "CCL20 attracts CCR6+ cells such as dendritic cells (DCs) and CD4+ TH17 cells that migrate along the CCL20 gradient to the site of infection." (PMID 33659876, 2021). "Further RT-PCR analyses determined that the levels of IFNB1, IFIT2, IFIT1, TNF and the proinflammatory cytokines CCL20 and IL6 were enhanced by RTN3 knockdown during VSV infection, while the amplification of VSV was compromised." (PMID 34313226, 2021). "Despite the differences in the magnitude of induction between each HBEC donor, combined, we observed a consistent trend of proinflammatory cytokine and chemokine (CCL2, CCL20, CXCL6, IL-6 and TNFα) inductions within 24 h post-infection with SARS-CoV-2." (PMID 34452468, 2021). "After 1 day of infection, the oral tissues of the gefitinib-treated mice contained significantly less CXCL1/KC, CCL20, IL-1α, IL-1β, IL-17A, and the host defense peptide S100A8 than control mice." (PMID 33471869, 2021). "CXCL5 levels tended to be higher in BALF of Dnmt3bfl/flCc10Cre mice relative to control mice at 6 hours post-infection (P = 0.07); BALF CCL20 concentrations were similar in Dnmt3bfl/flCc10Cre and control mice." (PMID 33793661, 2021). "SIV transmission via vaginal mucosal challenge has been shown to induce MIP-3α/CCL20 signaling in endocervix in combination with innate immune and inflammatory responses to infection in both cervix and vagina." (PMID 34093520, 2021). "Treatment of mice with gefitinib inhibited C. albicans-induced phosphorylation of both EphA2 and EGFR in the oral epithelial cells, and reduced the tissue levels of CXCL1/KC, CCL20, and S100A8 after both 1 and 2 days of infection." (PMID 33471869, 2021). "In SGPV-infected gills we see a coordinated suppression of CCL20 and IL-22 in the early phase of infection (E-III), and the γδ T-cell marker TCR Fcγ, is also suppressed during the peak of infection." (PMID 33013908, 2020). "IECs respond to bacterial invasion by releasing IL-8 and CCL20, a pivotal step in the recruitment of granulocytes and CCR6+ lymphocytes (Th17 and Th1/17 cells) to the site of infection." (PMID 32752244, 2020). "Of these 7 cytokines/chemokines, only 4 were expressed in wild type at relatively low concentrations, while 3 (CCL20, CCL17, CXCL1) appeared to be uniquely expressed in Nlrx1-/- mice at this early stage of infection." (PMID 32956405, 2020). "Further, comparative analysis of animals with different severity to infection highlights the potential importance of genes such as perforin-1, ENPP2 and CCL20 in conferring higher resistance against AGD." (PMID 30873203, 2019). "(d) Serum levels of the cytokines IL-1β, IL-10, CCL20 and CXCL2 2 hr after infection by CC17 GBS (n = 9 mice per group)." (PMID 31710290, 2019).
infection (continued). "This unique chemokine profile targets different populations of immune cells like dendritic cells, T cells, and B cells by CCL20, neutrophils by CXCL1 to CXCL3, and macrophages and T-cells by CCL2 to the site of infection." (PMID 29726306, 2018). "Differential changes in the expression of CCL19, CCL20, IL-8, IL-15, and Trail/TNF (ligand) superfamily members TNFSF10 and TNFSF15 in DT40 cells were also observed at different time points after vvIBDV infection." (PMID 28086922, 2017). "Infection with Ccr6tg virus restored CCR6 expression in activated γδT17 cells, which regained the ability to migrate toward CCL20." (PMID 28580944, 2017). "Based on microarray analyses, expression of cytokines and chemokines such as CCL20 and CXCL8 was shown to be increased upon E. coli 1303 infection 514 and 58-fold, respectively." (PMID 26062913, 2015). "Our data clearly show an increased expression of a set of chemokines (CCL20, CCL5, CXCL1, CXCL10, CXCL11, CCL25) normally involved in H. pylori gastritis at both 6 and 18 weeks of infection in mice, which decreased after curcumin treatment." (PMID 25569625, 2015). "Post albendazole and/or praziquantel treatment, the cellular release of IL-10, IL-33, MIP3-α/CCL20 and MIG/CXCL9 lessened significantly in all children infection groups." (PMID 25698903, 2015). "In vivo studies on bacterial infections have, so far, been limited to a description of an increase of CCL20 and CCR6-positive cells at the site of infection." (PMID 24699535, 2014). "those that are highly upregulated only by infection with virulent S. flexneri (CCL4, CCL20, IFN-γ, IL-1β, IL-4, IL-6, IL-8, IL-12/23p40, IL-21, TNF-α, CAP-18, LeukoP and COX-2); ii." (PMID 22675469, 2012). "The quantification of DC recruiters IP-10 (CXCL10), MIP-3α (CCL20) and BRAK (CXCL-14) by ELISA or qPCR in P2Y2+/+ and P2Y2−/− BALFs confirmed lower expression of BRAK at day 10 post-infection in the P2Y2−/− BALFs compared to P2Y2+/+ BALFs." (PMID 23185614, 2012). "major immune response we monitored the expression of the CCR6 ligand CCL20 and the number of CD4+CCR6+ cells in the draining lymph nodes during the early phase of infection in B6.WT mice." (PMID 23028548, 2012). "On the other hand, pre-treatment with SB203580 (10 μM) resulted in significant reduction in the up-regulation of only CCL20 and SLPI genes upon B. pseudomallei KHW infection compared to controls (p<0.05)." (PMID 19806192, 2009). "Correspondingly, CCL20 was significantly up-regulated at 24 h, 48 h and 72 h post infection (p<0.05) and SLPI was significantly up-regulated at 48 h and 72 h post infection (p<0.05)." (PMID 19806192, 2009). "The expression of the antimicrobial peptide genes, lysozyme, CCL20 and SLPI, at 4 h, 24 h, 48 h and 72 h post infection was determined using qRT-PCR." (PMID 19806192, 2009). "Pre-incubation of the epithelial cells with BAY11-7082 (10 μM) significantly impaired the up-regulation of all three CCL20, lysozyme and SLPI genes upon B. pseudomallei KHW infection compared to untreated cell controls (p<0.05)." (PMID 19806192, 2009). "Spatial imaging localized CCL20-producing cells to wound-like gaps in mock and CDI-treated colonoids, identifying a repair-associated niche active independent of infection." (PMID 42239244, 2026). "In our efforts to uncover its role, we reveal that osteoblasts and macrophages secrete CCL20 in response to infection, and mice lacking CCL20 or its monogamous receptor CCR6 are more susceptible to S." (PMID 40853122, 2025). "In TB, upregulation of CCL20 has been observed in response to Mtb antigens, mediated by TNF-α/IFN-γ and the MAPK/NF-κB pathways, suggesting a role in immune cell recruitment during active infection." (PMID 40575568, 2025). "Moreover, infection with SFV/IFNγ specifically inhibited GM-CSF, CCL20 and CXCL5 compared to the SFV group (p < 0.0001)." (PMID 40547518, 2025).
infection (continued). "Many up-regulated genes are closely related to inflammation and immune responses, such as CCL20, IL6, CXCL1, CSF1R, CCR5, TNFRSF8, indicating that mice infected N. farcinica via these two infection routes may lead to robust inflammatory response." (PMID 40723822, 2025). "Namely, CD5, CD8A, CD6 and CD244, C-C and C-X-C motif chemokines (CXCL5 CXCL6, MCP-4, and CCL20), as well as CD40, PDL-1, CUB domain-containing protein 1 (CDCP1) and interleukin-12B (IL-12B) were elevated in the late infection group compared to the unexposed group." (PMID 41510260, 2025). "Histological findings of immune cell infiltration in tracheal tissues after infection with swH1N1 was in line with induction of cytokines and chemotactic factors (AMCF-II, CXCL8/IL8, CXCL2, CXCL10, and CCL20) as well as receptors (CCR1 and CXCR2) in lower trachea after this infection." (PMID 39247193, 2024). "However, at 30 days post-infection, TNF-α, IL-6, KC, CCL3, CCL2, CCL20, CXCL11, CCL11), CCL27, CXCL5, CXCL12 and CCL5 were all significantly higher in the BAL fluid of Duox1 KO compared to WT mice." (PMID 36936954, 2023). "Results showed that pretreatment with 1,25(OH)2D3 significantly suppressed IL-8, IL-19, and CCL20 mRNA expression induced by PEDV at 1 h post-infection, but did not decrease p-NF-κB protein levels." (PMID 36142545, 2022). "Furthermore, Dnmt3bfl/flSpCcre and control mice showed similar CXCL5, CCL20, IL-1β and TNF-α BALF levels upon infection with PAK." (PMID 33793661, 2021). "The genes, Ccl2, Ccl20, Csf1, Cx3cl1, Cxcl1, Cxcl3, Il6, Birc3, Map3k8, Nos2, Nfkb2, Tnfrsf1b, and Vcam1, played core roles in a PPI network, and interacted closely with other ones in the infection." (PMID 33042984, 2020). "We report a strong induction of numerous pro-inflammatory cytokines, chemokines and AMPs such as CXCL1, CXCL2, CXCL5, CXCL8, CCL20, TNFα, TSLP, IL-23α, IL-32, IL-6, hBD2 and S100A7 during the infection of monolayered primary keratinocytes and reconstructed epidermis with the wild-type PAK strain." (PMID 30070169, 2018). "From these findings and our current findings, we can conclude that the role of CCL20 is probably to control pathogen infection after wounding, rather than wound closure." (PMID 28815185, 2017). "In contrast, CCL20 mRNA that is expressed in human gingival epithelial cells at 16 h after infection with P. gingivalis is blocked by inhibiting p38, but not JNK." (PMID 27058037, 2016). "Using cells only treated with IL-33 or cells only infected with HTNV as controls, the mRNA expression of IL-1β, IL-6, IL-8, CCL2, CCL20, CXCL1, CXCL2, and CX3CL1 was significantly induced in HUVECs prior to infection with HTNV (MOI = 1) for 48 h and then exposed to IL-33 (20 ng/ml) for 6 h." (PMID 25658420, 2015). "Irrespective of the children infection groups G0, G1, G3+, the release of MIP3-α/CCL20 remained at similar levels when PBMC were activated with D. pteronyssinus (Dp) and A. fumigatus (Af)." (PMID 25698903, 2015). "In order to investigate the effect of statins on the expression of infection-responsive, immunomodulatory genes, 5 genes previously shown to be induced during P. aeruginosa infection were selected for analysis; KLF2, KLF6, IL-8, TLR5 and CCL20." (PMID 25010049, 2014). "Compared to uninfected controls at day 7, infection of non-Tg mice with C. albicans significantly (p < 0.05) enhanced tongue tissue expression of S100a8, Ccl20, Il17, Il22 and, to a lesser degree, of the Dfb3 gene." (PMID 25344377, 2014). "In addition, PR/8 infection up-regulated mRNA expression of many chemokine genes including CC chemokines CCL2–5, and CCL20, as well as CXC chemokines CXCL9–11." (PMID 22396727, 2012).